F2RL1 (F2R like trypsin receptor 1)
Description:
Receptor for trypsin and trypsin-like enzymes coupled to G proteins. Its function is mediated through the activation of several signaling pathways including phospholipase C (PLC), intracellular calcium, mitogen-activated protein kinase (MAPK), I-kappaB kinase/NF-kappaB and Rho. Can also be transactivated by cleaved F2R/PAR1. Involved in modulation of inflammatory responses and regulation of innate and adaptive immunity, and acts as a sensor for proteolytic enzymes generated during infection. Generally is promoting inflammation. Can signal synergistically with TLR4 and probably TLR2 in inflammatory responses and modulates TLR3 signaling. Has a protective role in establishing the endothelial barrier; the activity involves coagulation factor X. Regulates endothelial cell barrier integrity during neutrophil extravasation, probably following proteolytic cleavage by PRTN3. Proposed to have a bronchoprotective role in airway epithelium, but also shown to compromise the airway epithelial barrier by interrupting E-cadherin adhesion. Involved in the regulation of vascular tone; activation results in hypotension presumably mediated by vasodilation. Associates with a subset of G proteins alpha subunits such as GNAQ, GNA11, GNA14, GNA12 and GNA13, but probably not with G(o)-alpha, G(i) subunit alpha-1 and G(i) subunit alpha-2. However, according to PubMed:21627585 can signal through G(i) subunit alpha. Believed to be a class B receptor which internalizes as a complex with arrestin and traffic with it to endosomal vesicles, presumably as desensitized receptor, for extended periods of time. Mediates inhibition of TNF stimulated JNK phosphorylation via coupling to GNAQ and GNA11; the function involves dissociation of RIPK1 and TRADD from TNFR1. Mediates phosphorylation of nuclear factor NF-kappa-B RELA subunit at 'Ser-536'; the function involves IKBKB and is predominantly independent of G proteins. Involved in cellular migration. Involved in cytoskeletal rearrangement and chemotaxis through beta-arrestin-promoted scaffolds; the function is independent of GNAQ and GNA11 and involves promotion of cofilin dephosphorylation and actin filament severing. Induces redistribution of COPS5 from the plasma membrane to the cytosol and activation of the JNK cascade is mediated by COPS5. Involved in the recruitment of leukocytes to the sites of inflammation and is the major PAR receptor capable of modulating eosinophil function such as pro-inflammatory cytokine secretion, superoxide production and degranulation. During inflammation promotes dendritic cell maturation, trafficking to the lymph nodes and subsequent T-cell activation. Involved in antimicrobial response of innate immune cells; activation enhances phagocytosis of Gram-positive and killing of Gram-negative bacteria. Acts synergistically with interferon-gamma in enhancing antiviral responses. Implicated in a number of acute and chronic inflammatory diseases such as of the joints, lungs, brain, gastrointestinal tract, periodontium, skin, and vascular systems, and in autoimmune disorders. Probably mediates activation of pro-inflammatory and pro-fibrotic responses in fibroblasts, triggered by coagulation factor Xa (F10) (By similarity). Mediates activation of barrier protective signaling responses in endothelial cells, triggered by coagulation factor Xa (F10).
Synonyms: GPR11; PAR2
Tractability: Small molecule: a structure with a bound ligand is known; a high-quality ligand is known; it belongs to a druggable protein family. Antibody: its Gene Ontology location is reachable by antibodies, with high confidence; UniProt places it where antibodies can reach, with medium confidence; UniProt predicts a signal peptide or a membrane-spanning region; the Human Protein Atlas places it where antibodies can reach. PROTAC: UniProt records ubiquitination sites on it; ubiquitination databases record sites on it; a small molecule that binds it is known.
Target class: Protease-activated receptor; Membrane receptor; Peptide receptor (family A GPCR); Family A G protein-coupled receptor
Gene: Protein-coding gene on chromosome 5 (76,818,933 to 76,835,315, forward strand). Ensembl gene ENSG00000164251.
Subcellular location: Cell membrane
Subcellular location (Human Protein Atlas): Plasma membrane
Pathways (Reactome):
Signal Transduction: G alpha (q) signalling events; Peptide ligand-binding receptors
Gene Ontology:
Molecular function: G protein-coupled receptor activity; protease binding; protein binding; G-protein alpha-subunit binding; G-protein beta-subunit binding; signaling receptor activity; signaling receptor binding; proteinase-activated receptor activity; thrombin-activated receptor activity
Biological process: antimicrobial humoral response; cell-cell junction maintenance; defense response to virus; establishment of endothelial barrier; G protein-coupled receptor signaling pathway; leukocyte migration; mature conventional dendritic cell differentiation; negative regulation of chemokine production; negative regulation of JNK cascade; negative regulation of toll-like receptor 3 signaling pathway; negative regulation of tumor necrosis factor-mediated signaling pathway; neutrophil activation; positive regulation of actin filament depolymerization; positive regulation of canonical NF-kappaB signal transduction; positive regulation of chemokine production; positive regulation of cytokine production involved in immune response; positive regulation of cytosolic calcium ion concentration; positive regulation of eosinophil degranulation; positive regulation of ERK1 and ERK2 cascade; positive regulation of interleukin-1 beta production; positive regulation of interleukin-10 production; positive regulation of interleukin-6 production; positive regulation of interleukin-8 production; positive regulation of JNK cascade; positive regulation of leukocyte chemotaxis; and 24 more
Cellular component: early endosome; plasma membrane; Golgi apparatus; pseudopodium; membrane
Genetic constraint (gnomAD): Loss-of-function variants: 15 observed, 23.36 expected, observed/expected ratio (o/e) 0.64, 90% interval 0.43 to 0.99. The upper end of that interval is the gene's LOEUF score, 0.99, which puts it in group 4 of 6, group 1 being the genes least tolerant of losing a copy. Missense variants: 429 observed, 491.68 expected, observed/expected ratio (o/e) 0.87, 90% interval 0.81 to 0.94. Synonymous variants: 181 observed, 192.9 expected, observed/expected ratio (o/e) 0.94, 90% interval 0.83 to 1.06.
Homologues: Orthologues: chimpanzee F2RL1 (99% identical), macaque F2RL1 (95% identical), pig F2RL1 (89% identical), dog F2RL1 (84% identical), mouse F2rl1 (84% identical), rat F2rl1 (83% identical), rabbit F2RL1 (82% identical), guinea pig F2RL1 (81% identical), tropical clawed frog f2rl1 (60% identical), zebrafish f2rl1.2 (49% identical), zebrafish f2rl1.1 (47% identical). Paralogues in human: F2R (34% identical), F2RL3 (29% identical), F2RL2 (29% identical), P2RY8 (27% identical), GPR17 (23% identical), GPR20 (23% identical), GPR65 (23% identical), GPR18 (22% identical), P2RY10 (22% identical), GPR4 (21% identical), CYSLTR2 (21% identical), CYSLTR1 (21% identical), and 4 more.